RTP3 (receptor transporter protein 3)
Description:
Promotes functional cell surface expression of the bitter taste receptors TAS2R16 and TAS2R43.
Synonyms: TMEM7; Z3CXXC3; LTM1
Tractability: Antibody: UniProt predicts a signal peptide or a membrane-spanning region.
Gene: Protein-coding gene on chromosome 3 (46,494,611 to 46,500,950, forward strand). Ensembl gene ENSG00000163825.
Subcellular location: Membrane
Subcellular location (Human Protein Atlas): Mitochondria
Gene Ontology:
Molecular function: protein binding; olfactory receptor binding
Biological process: detection of chemical stimulus involved in sensory perception of bitter taste; protein targeting to membrane; protein insertion into membrane
Cellular component: cytoplasm; membrane
Genetic constraint (gnomAD): Loss-of-function variants: 2 observed, 6.31 expected, observed/expected ratio (o/e) 0.32, 90% interval 0.13 to 1. That is too few expected variants to judge how well the gene tolerates losing a copy. Missense variants: 252 observed, 296.25 expected, observed/expected ratio (o/e) 0.85, 90% interval 0.77 to 0.94. Synonymous variants: 106 observed, 104.45 expected, observed/expected ratio (o/e) 1.01, 90% interval 0.87 to 1.19.
Homologues: Orthologues: chimpanzee RTP3 (99% identical), macaque RTP3 (91% identical), dog RTP3 (61% identical), mouse Rtp3 (52% identical), rat Rtp3 (51% identical). Paralogues in human: RTP4 (38% identical), RTP2 (29% identical), RTP1 (27% identical), RTP5 (26% identical).
Diseases named in the same sentence as RTP3 in open-access papers:
RTP3 is named in the same sentence as 15 diseases in open-access papers, as found by Europe PMC text mining. Sharing a sentence is not in itself a finding about the gene and the disease. The quoted sentences say what the papers report.
viral infection (2 papers, 2018 to 2021). "Black flying fox RTP3 (paRTP3) was the only RTP other than the RTP4 homologs that inhibited viral infection." (PMID 34014925, 2021).
fracture (1 paper, 2010). "The significant association of a nearby common SNP (rs10514713) (MAF = 42.9%) with hip fracture (P = .001) provides supportive evidence for the potential importance of the RTP3 gene to the risk of hip fracture." (PMID 20175129, 2010).
hip fracture (1 paper, 2010). Traumatic or pathological injury to the hip in which the continuity of either the femoral head, femoral neck, intertrochanteric or subtrochanteric regions is broken. "In addition, 350 hip fracture patients and 350 healthy control individuals were genotyped to assess the association of the RTP3 gene with the risk of hip fracture." (PMID 20175129, 2010).
renal cell carcinoma (1 paper, 2015). "RTP3 showed similarity to zf-3CxxC transcription regulators family, previously reported to be involved in renal cell carcinoma." (PMID 26169495, 2015).
steatosis (1 paper, 2021). Increased lipid within the cytoplasm of cells. "RTP3 in the yellow module was in high expression for steatosis and NASH samples, while RASD1 in the yellow module was in low expression for steatosis and NASH samples." (PMID 34041361, 2021).
tumor (7 papers, 2015 to 2025). "Although RTP3 was significantly down-regulated in our tumor set, we did not observe any relevance of this down-regulation in respect to clinical and molecular tumor characteristics." (PMID 26169495, 2015). "TMEM expression was also dependent on tumor invasion to space surrounding a nerve for ANO1, TMEM116, and TMEM97 (p = 0.002, p < 0.0001, p = 0.008) and on angiolymphatic invasion for TMEM48, RTP3, TMEM173, and TMEM116 (p < 0.0001, p = 0.0267, p = 0.001, p = 0.0053, respectively)." (PMID 34638224, 2021).
infection (5 papers, 2020 to 2024). The state of being infected such as from the introduction of a foreign agent such as serum, vaccine, antigenic substance or organism. "The rtp3 gene shows an extraordinary sensitivity to NNV since its up-regulation is highly stimulated soon after infection, appearing to be linked to the resistance to infection." (PMID 34064461, 2021). "The most induced genes after NNV infection with the wt virus were VRGs, particularly RTP3, SACS, and TRIM39." (PMID 35215144, 2022). "Regarding the IFN-I system-related genes, irf3 and rtp3 transcription was up-regulated following the infection with both viruses, although differences regarding the intensity and/or the temporal profile of the induction were observed when the results from both experimental groups were compared." (PMID 38921776, 2024). "Moreover, rtp3 is the only analysed gene that was up-regulated by infection at 1 dpi." (PMID 38921776, 2024).
RTP3 also shares sentences with these, for which no sentence is quoted: hepatocellular carcinoma (5 papers); cancer (3); lymphoma (2); clear cell renal cell carcinoma (1); colorectal cancer (1); glioma (1); idiopathic interstitial pneumonia (1); lung carcinoma (1).